SPHK1 (sphingosine kinase 1)
Diseases named in the same sentence as SPHK1 in open-access papers (continued):
Sharing a sentence is not in itself a finding about the gene and the disease.
Myocardial fibrosis (2 papers, 2022 to 2023). "Disruption of SPHK1 markedly improved myocardial fibrosis and cardiac dysfunction after MI and attenuated ER stress and inflammatory response in cardiomyocytes." (PMID 37773702, 2023). "Compared with the AAV‐sh‐NC group, the infarct area and myocardial fibrosis levels were reduced in the AAV‐sh‐SPHK1 group." (PMID 37773702, 2023). "Therefore, the pro‐fibrotic properties of SPHK1 were substantiated, and the specific downstream pathway through which SPHK1 regulated myocardial fibrosis awaits further exploration." (PMID 37773702, 2023). "Consistently, infarct size and myocardial fibrosis levels were reduced in mice with ATF3 downregulation, while SPHK1 overexpression decreased the anti‐fibrotic effect of ATF3 downregulation in MI mice." (PMID 37773702, 2023).
nasopharyngeal carcinoma (2 papers, 2016 to 2022). A carcinoma arising from the nasopharyngeal epithelium. "We previously demonstrated that SPHK1 is overexpressed and associated with clinical stage, locoregional recurrence, distant metastasis and poor prognosis in nasopharyngeal carcinoma (NPC)." (PMID 27811359, 2016).
non-alcoholic steatohepatitis (2 papers, 2022 to 2023). "The association between SphK1 and hepatic inflammation was also demonstrated in a mouse model of non-alcoholic steatohepatitis, where high saturated fat feeding initiated proinflammatory signalling in hepatocytes through the SphK1/S1P/S1PR1 pathway." (PMID 35158806, 2022).
peritonitis (2 papers, 2012 to 2019). Inflammation of the peritoneum (tissue that lines the abdominal wall and covers most of the organs in the abdomen). "For instance, a study published in 2006 showed that SphK1 is not required for inflammatory cell recruitment during thioglycollate-induced peritonitis." (PMID 22615770, 2012).
pituitary tumor (2 papers, 2023 to 2025). A benign or malignant neoplasm affecting the pituitary gland. "The knockdown of SPHK1 suppresses S1P-mediated cell proliferation in GH3 cells by promoting autophagy and apoptosis with inhibition of GH secretion, which suggests that SIPR2 may be a promising therapeutic target for GH-secreting pituitary tumors." (PMID 40361329, 2025).
pulmonary edema (2 papers, 2012 to 2022). Accumulation of fluid in the lung tissues causing disturbance of the gas exchange that may lead to respiratory failure. "In addition, an interesting study where bone marrow derived progenitor cells (BMPC) were used to improve LPS induced pulmonary edema revealed that BMPC from SphK1−/− mice did not provide similar protection." (PMID 22615770, 2012).
rectal cancer (2 papers, 2017 to 2025). A primary or metastatic malignant neoplasm that affects the rectum. "We found that in the TCGA colon and rectal cancer data, the RNA expression of SPHK1 and SGPL1 were positively correlated with the extent of macrophage infiltration in the tumor microenvironment, but not with T cells or B cells." (PMID 40589755, 2025).
Right ventricular hypertrophy (2 papers, 2016 to 2022). In this case the right ventricle is more muscular than normal, causing a characteristic boot-shaped (coeur-en-sabot) appearance as seen on anterior- posterior chest x-rays. "In contrast, RB-005 lacked effects on right ventricular hypertrophy, suggesting that sphingosine kinase 1 inhibition might be nullified by concurrent inhibition of ceramide synthase." (PMID 27063355, 2016). "Further, the inhibition of SPHK1 reduced S1P levels and occlusive pulmonary arteriopathy without reducing RVSP or right ventricular hypertrophy." (PMID 36498853, 2022).
steatosis (2 papers, 2020 to 2024). Increased lipid within the cytoplasm of cells. "Thus, during the transition from steatosis to hepatitis, certain factors stimulate LSECs, leading to an increase of SphK1 and S1P production." (PMID 38753743, 2024). "Only one clinical study has shown SphK1 expression increase in liver biopsies from patients with steatosis compared to healthy lean people, which supports the notion that SphK1/S1P axis could play a role in the onset of these diseases." (PMID 32668665, 2020). "This indicates that steatosis does not induce SphK1 induction." (PMID 38753743, 2024). "By contrast, mice displaying a liver-specific overexpression of SphK1 via the use of an adeno-associated-viral (AAV) 8, whose tropism is specific of the liver, exhibited reduced hepatic triglyceride levels (steatosis) without affecting glucose metabolism on a low-fat diet." (PMID 32668665, 2020).
tongue squamous cell carcinoma (2 papers, 2014 to 2024). A squamous cell carcinoma that arises from the tongue. "Invasion assays were used to measure invasive ability of SphK1 overexpressing human tongue squamous cell carcinoma (SCC-25 cells)." (PMID 25197261, 2014). "Subsequently, to explore the downstream signaling pathway regulating PD-L1 expression induced by SPHK1 in HNSCC, we selected fresh tumor tissues from nine patients with tongue squamous cell carcinoma before immunotherapy for RNA sequencing (RNA-seq) analysis." (PMID 39629135, 2024). "To investigate whether MAPK family members are involved in the regulation of MMP1 by SPHK1, we performed gene set enrichment analysis (GSEA) of SPHK1 using RNA-seq data from fresh tumor tissues obtained from nine patients with tongue squamous cell carcinoma before immunotherapy." (PMID 39629135, 2024).
acute lymphoblastic leukemia (1 paper, 2017). Leukemia with an acute onset, characterized by the presence of lymphoblasts in the bone marrow and the peripheral blood. "Furthermore, S1P inhibits classical apoptosis in T acute lymphoblastic leukemia (T-ALL) and SPHK1 level is increased in B-ALL, contributing to the development of murine BCR/ABL1 ALL." (PMID 29216917, 2017).
adrenal cancer (1 paper, 2016). A carcinoma involving a adrenal gland. "To confirm whether SphK1 regulates cell proliferation in ACC, we using siRNA to knockdown SphK1 expression in the two adrenal cancer cell lines, SW13 and H295R." (PMID 26673009, 2016).
amyloid (1 paper, 2014). "Immunohistochemical analysis revealed a decreased expression of SphK1 and an increased expression of SPL both correlated to amyloid deposits in the entorhinal cortex." (PMID 24468113, 2014).
Atopic Dermatitis (1 paper, 2024). "Here, we conducted a clinical trial to evaluate the efficacy of a multi-lamellar emulsion (MLE) containing the pseudoceramide PC-9S and a synthetic sphingosine kinase 1 (SPHK1) activator, DefensamideTM, in improving mild-to-moderate atopic dermatitis." (PMID 39212849, 2024).
Atrophy (1 paper, 2023). Any weakening or degeneration, especially through lack of use. "SphK1/S1P/S1PR2 signaling axis is activated in dexamethasone-induced muscle atrophy, while SphK1/S1P/S1PR3 signaling axis is activated in TNF-α induced muscle atrophy." (PMID 37852968, 2023).
B-cell non-Hodgkin lymphoma (1 paper, 2014). The most common type of non-Hodgkin lymphoma. "SPHK1, which catalyzes S1P production within the cells, was more frequently expressed in B-cell non-Hodgkin lymphomas with higher clinical grade." (PMID 25472725, 2014).
bowel cancer (1 paper, 2021).
cerebral amyloid angiopathy (1 paper, 2018). "In APP/PS1/SphK1 tg mice, cerebral amyloid angiopathy also was reduced." (PMID 29662056, 2018).
cerebral infarct (1 paper, 2021). "Results showed that DSCXQ intervention significantly reduced cerebral infarct size, ameliorated behavioral abnormality, inhibited the expression of Sphk1, S1PR1, CD62P, Bax, Cleaved Caspase-3, while increased the level of Bcl-2, and prevented neuronal apoptosis." (PMID 34026822, 2021).
chlamydial infection (1 paper, 2025). "Following up on the observation that SPHK1 transcript levels increase after chlamydial infection of professional phagocytes, we next tested the enzymatic activity of SPHK." (PMID 40249190, 2025).
chronic kidney disease (1 paper, 2020). Impairment of the renal function secondary to chronic kidney damage persisting for three or more months. "SphK1/S1P pathway is implicated in the progression of chronic kidney disease." (PMID 32393187, 2020). "The findings from the present study together with other reports suggest that SphK1/S1P acts on kidney cells to produce renal injuries in chronic kidney diseases bypassing its regulation in immune response." (PMID 32393187, 2020).
chronic lung disease (1 paper, 2025). According to the definitions of the American and British Thoracic Societies, including pulmonary functional tests, X-rays, and CT scans for items such as fibrosis, bronchiectasis, bullae, emphysema, nodular or lymphomatous abnormalities. "S1P, a bioactive lysophospholipid synthesized by sphingosine kinase 1 (SPHK1), plays a crucial role in various biological processes and diseases, including both acute and chronic lung diseases." (PMID 40969747, 2025).
clear cell carcinoma (1 paper, 2021). "In the subgroup of clear cell carcinoma (n = 165, 16.4%), low SPHK1 expression was detected significantly more often (low SPHK1 in 88.5%, high SPHK1 in 11.5%) than in all other histological subtypes (p < 0.001)." (PMID 33660008, 2021). "While there was no conclusive correlation of HGSO with SPHK1 expression in our patient collective, we found a distinct correlation of low SPHK1 expression with the histological subtype of clear cell carcinoma." (PMID 33660008, 2021). "Nevertheless, a distinct trend for a better PFS and OS could not be pointed out for high expression of SPHK1 in the subgroup of clear cell carcinoma." (PMID 33660008, 2021).
clear cell ovarian carcinomas (1 paper, 2021). "Low levels of SPHK1 expression were mainly present in the histological subtype of clear cell ovarian cancer with 88.5% of all clear cell OC revealing low SPHK1 expression." (PMID 33660008, 2021). "Nevertheless, Kaplan–Meier analysis of the subgroup of clear cell ovarian carcinomas (n = 165) did not reveal any distinct trend for better PFS or OS in patients with high SPHK1 expression (p = 0.754 and p = 0.474, respectively)." (PMID 33660008, 2021).
cystitis (1 paper, 2025). Inflammation of the urinary bladder. "Bladder tissue S1P levels were elevated in CYP-induced cystitis mice, whereas knockdown of SPHK1 reduced S1P levels." (PMID 39578076, 2025).
diabetic cardiomyopathy (1 paper, 2022). Diabetic cardiomyopathy is a disorder of the heart muscle in people with diabetes. "Our study showed that the S1P-SphK1 pathway is one of the prominent role players of diabetic cardiac fibrosis; thus, suppressing the SphK1 gene expression can be considered a potential means to prevent diabetic cardiomyopathy." (PMID 35414826, 2022). "We also showed that decreasing SphK1, the source of the S1P, with aminoguanidine could be a novel approach to preventing diabetic cardiomyopathy." (PMID 35414826, 2022).
diabetic retinopathy (1 paper, 2019). "In addition, S1P has been proposed to signal through S1PRs, in a paracrine fashion, upregulating the transcription of SphK1 and thus activating the S1P/SphK1 axis; this “outside-in” signaling pathway has been shown to contribute to the progression of diabetic retinopathy." (PMID 31244608, 2019).
emphysema (1 paper, 2013). "Concomitant treatment with S1P normalizes the ceramide-S1P balance in the rat lungs and increases HIF-1α protein expression via activation of sphingosine kinase 1; as a consequence, S1P salvages fenretinide induced emphysema in rat lungs." (PMID 23326540, 2013).
endometrioid ovarian carcinoma (1 paper, 2021). "In the subgroup analysis of endometrioid ovarian cancer (n = 155, 15.4%), low SPHK1 expression was detected more often than high expression (low SPHK1 in 68.4%, high SPHK1 in 31.6%)." (PMID 33660008, 2021). "Further studies are needed to differentiate between estrogen receptor-negative and -positive subtypes of endometrioid ovarian cancer to elucidate the association with SPHK1 expression and survival." (PMID 33660008, 2021).
epilepsy (1 paper, 2020). A brain disorder characterized by episodes of abnormally increased neuronal discharge resulting in transient episodes of sensory or motor neurological dysfunction, or psychic dysfunction. "In the future, we will perform experiments in different animal species and animal seizure models, and further to investigate the effect of SphK1/S1PR2 signal specific inhibitor and agonists on molecules associated with epilepsy." (PMID 33134289, 2020).
female infertility (1 paper, 2022). Diminished or absent ability of a female to achieve conception. "Specifically depleting Sphk1/2 in somatic cells reduced S1P levels and impaired oocyte meiotic maturation and developmental competence, resulting in complete female infertility." (PMID 36396932, 2022).
gallbladder cancer (1 paper, 2018). "Finally, immunohistochemical examination revealed that gallbladder cancer with lymph node metastasis had significantly higher expression of phospho-SPHK1 than that without." (PMID 30018456, 2018).
gastric ulcer (1 paper, 2014). An ulcerated lesion in the mucosal surface of the stomach. "We also found that the deficiency of SphK1(not SphK2) significantly inhibits gastric ulcer, indicating that SphK1 may play a pivotal role in gastric ulcer." (PMID 24454691, 2014).
glomerulosclerosis (1 paper, 2020). A hardening of the kidney glomerulus caused by scarring of the blood vessels. "Sphk1/S1P was shown to induce pro-fibrotic factors production by cross-activating the TGF-β/Smad signaling pathway, and over-expression of Shpk1 promoted the release of inflammatory factors leading to glomerulosclerosis and interstitial fibrosis." (PMID 33231567, 2020).
Hashimoto thyroiditis (1 paper, 2023). An autoimmune disorder caused by the production of autoantibodies against thyroid tissue. "In CD4 + T cells in Hashimoto thyroiditis, increased SphK1 produces more S1P, which activates the S1PR1-JAK2-STAT3 and S1PR1-mTOR-STAT3 pathways." (PMID 37858140, 2023).
hematoma (1 paper, 2024). A hematoma is a collection of blood from a vascular structure into an extravascular space. "Importantly, we found that inhibition of Sphk1/S1P with PF543 substantially decreased the hematoma volume and brain water content in the ICH + PF543 group compared to the ICH + Vehicle group." (PMID 39715736, 2024). "Our findings reveal a significant upregulation of Sphk1 in peri-hematomal endothelial cells in both human and murine ICH, which was attenuated by Sphk1 inhibition, subsequently reducing hematoma volume, brain edema, and neurological deficits." (PMID 39715736, 2024). "Pharmacological inhibition of Sphk1 with PF543 attenuates BBB leakage, reduces hematoma volume, and improves neurological outcomes in mice." (PMID 39715736, 2024).
hepatoblastoma (1 paper, 2018). Hepatoblastoma (HB) is a malignant hepatic tumor and is the most common pediatric liver cancer. "The downregulation of SphK1 in HCC cell lines, including hepatoblastoma G2 and HCC-9724, has indicated that cell proliferation is decreased in the absence of SphK1, providing evidence that Sphk1 promotes HCC cell proliferation and is involved in tumor progression." (PMID 29510489, 2018).
HIV-1 infection (1 paper, 2022). The type species of lentivirus and the etiologic agent of acquired immunodeficiency syndrome (AIDS). "As SPHK inhibition, in addition to S1PR modulation with FTY720, hinders HIV-1 cell-to-cell transmission, our results suggest that SPHK1 and SPHK2 are involved in HIV-1 infection of primary CD4 T cells and represent unique targets toward halting HIV-1 infection." (PMID 35412343, 2022).
Hypoglycemia (1 paper, 2025). A decreased concentration of glucose in the blood. "Following hypoglycemia, transient changes from baseline occurred in DKK1, cathepsin A, cathepsin G, cathepsin H, cathepsin S, cathepsin Z, parathyroid hormone (PTH), Sphingosine kinase 1 and 2 (SPK1/2), and interleukin-1 beta (IL1 beta) over the post-hypoglycaemia time course." (PMID 41373586, 2025).
immune deficiency (1 paper, 2020). "Exogenous S1P supplementation not only fully compensated the immune deficiency observed in sphingosine kinase (sphk-1) mutants, but also dramatically increased the resistance of wild type worms to pathogenic bacteria." (PMID 33105563, 2020).
Infertility (1 paper, 2022). "It is possible that low levels of S1P in somatic cells of Sphk1/2gc−/− mice decreased Akt/mTOR activity in oocytes, resulting in abnormal spindle assembly and then infertility." (PMID 36396932, 2022).
inflammatory bone diseases (1 paper, 2021). "Because inflammation stimulates the activation of SphK1 and the generation of S1P, high S1P and SphK1 levels are often observed in patients with inflammatory bone diseases." (PMID 33922596, 2021).
insulinoma (1 paper, 2024). "SphK1 knockdown in rat insulinoma INS-1 832/13 cells reduced insulin synthesis and secretion, whereas SphK1 overexpression restored them." (PMID 38256005, 2024).
Interstitial cardiac fibrosis (1 paper, 2017). A type of myocardial fibrosis characterized by excessive diffuse collagen accumulation concentrated in interstitial spaces. "In our recent study, we demonstrated that transgenic overexpression of SphK1 in mice resulted in interstitial cardiac fibrosis but not hypertrophy, which was mediated via S1PR3 but independent of AT1." (PMID 28771545, 2017).
intestinal inflammation (1 paper, 2016). "Growing evidence has demonstrated that S1P is linked to chronic intestinal inflammation and colitis-associated cancer, in which upregulation of Sphk1 is needed." (PMID 27050145, 2016).
intestinal tumor (1 paper, 2011). "Accordingly, overexpressing sphingosine kinase 1 (Sphk1), one of the main enzymes that catalyzes the formation of S1P, results in increased tumorigenic activity in the Min mouse model of intestinal tumor progression." (PMID 21569306, 2011).
invasive carcinoma (1 paper, 2022). A carcinoma that is not confined to the epithelium, and has spread to the surrounding stroma. "Previous studies confirmed that overexpression of SPHK1 was associated with decreased expression of E-cadherin and increased expression of vimentin, suggesting that SPHK1 plays a pivotal role in the EMT of invasive carcinoma cells." (PMID 35126792, 2022).
invasive ductal carcinoma (1 paper, 2017). "Interestingly, a comparison of the levels of SPHK1 gene revealed that the transcript expression in invasive lobular carcinoma (ILC) was 8.0-fold higher (p < 0.05) than in invasive ductal carcinoma (IDC) within the BC group." (PMID 29186783, 2017).
ischemia reperfusion injury (1 paper, 2023). Adverse functional, metabolic, or structural changes in ischemic tissues resulting from the restoration of blood flow to the tissue (reperfusion), including swelling; hemorrhage; necrosis; and damage from free radicals. "Additionally, in a study of murine kidneys, the A1AR agonist CCPA was found to protect against renal ischemia-reperfusion injury by inducing sphingosine kinase-1." (PMID 37513829, 2023).